MGMT (O-6-methylguanine-DNA methyltransferase)
Diseases named in the same sentence as MGMT in open-access papers (continued):
Sharing a sentence is not in itself a finding about the gene and the disease.
cancer (continued). "While such variants, in theory, may affect the cancer risk of individuals harboring them, to the best of our knowledge, germline pathogenic variants in the MGMT gene have never been reported; in case they exist, they must be rare." (PMID 39980037, 2025). "Additionally, cell-based assays and animal studies unveil the cancer prevention function of MGMT." (PMID 38254819, 2024). "Additionally, the identification of alkylated MGMT and MGMT inhibitors promoting the degradation of BRCA2 presents a promising strategy for targeting homologous recombination proficient cancers with MGMT inactivators in conjunction with DNA crosslinking agents." (PMID 38254819, 2024). "However, cancer cells have a mechanism to reverse the effect of temozolomide through the transcription and subsequent translation of the MGMT protein, which, through a sulfhydryl group, removes the methyl group from O6 methyl-guanine, restoring guanine to its original form." (PMID 39767683, 2024). "By delving deeper into the molecular underpinnings of MGMT, researchers may unlock new possibilities for the creation of targeted treatment regimens that can more effectively combat the multifaceted challenges posed by cancer." (PMID 39055560, 2024). "However, its action in direct DNA repair, which constitutes less than 10% of the damage inflicted by TMZ, as well as its relevance to the presence of RT alone and to other malignancies, and in the prevention of cancer development suggest a broader role of the MGMT promoter." (PMID 38612892, 2024). "However, cancer type and MGMT methylation status were not significant risk factors, indicating that RYK expression remained as a potential independent prognostic factor in this patient group." (PMID 37242509, 2023). "In general, MGMT is a small protein present not only in the nucleus but also in the cytoplasm, it repairs O6-alkylguanine adducts independently of any other protein or cofactors; thanks to its mechanism of action, MGMT is also able to protect cancer cells from chemotherapeutic alkylating agents." (PMID 37371106, 2023). "Thus, it has been shown that PARP inhibition enhances the toxic effect of TMZ in MGMT-proficient, but not in MGMT-deficient, cancer cells." (PMID 38068493, 2023). "In cancer therapy, several alkylating agents destroy cancer cells through the induction of DNA methylation, and some malignant cells resist these anti-malignant drugs partly by the increased production of DNA methylation enzymes, including MGMT, to counteract the DNA damage." (PMID 37373325, 2023). "However, a major mechanism that counteracts this cytotoxicity is the DNA repair enzyme, O6-methylguanine DNA methyltransferase (MGMT), which sequesters the toxic methyl adducts from O6 guanine prior to DNA replication, rendering the cancer cells resistant to TMZ cytotoxicity." (PMID 36619857, 2022). "This may possibly be explained by higher percentage of AML cases in the cohort, varying disease status (heterogeneity) at the time of HSCT and partly explained by the altered expression profiles of the MGMT and its regulation by methylation status of its promoter in cancer cells." (PMID 34711928, 2022). "Hence, the PARP1-MGMT protein complex could be targeted for the development of advanced and more effective cancer therapeutics, particularly for cancers sensitive to PARP1 and MGMT inhibition." (PMID 36242092, 2022). "Several studies examined O-6-methylguanine-DNA methyltransferase (MGMT) methylation, codeletion of chromosome arms 1p and 19q, and isocitrate dehydrogenase (IDH) mutations to provide insight into LGG pathogenesis and advance cancer therapies for patients with LGGs." (PMID 35879775, 2022).
cancer (continued). "Importantly, there was significant mutual-exclusiveness between MGMT hypomethylation, DNA hypermutation and MGMT fusion as revealed by a bootstrapping method (P < 10−4, see “Methods”), suggesting these alterations were carrying out alternative roles during cancer progression." (PMID 32753598, 2020). "As MGMT is methylated to 25% to 50% in numerous cancers, including brain, colon, lung, breast, gastric, and ovarian cancer, it involves the risk of offering positive results for cancer patients who were found negative for GBM." (PMID 31316555, 2019). "Thus, the ability to determine MGMT status accurately and efficiently in cancer cells could allow clinicians to tailor therapies to the needs of individual patients." (PMID 30811507, 2019). "Therefore, MGMT is considered as an attractive target for cancer chemotherapy." (PMID 30404161, 2018). "In addition, it has been reported that MGMT gene expression in normal and neoplatic tissues varies and MGMT promoter methylation was associated with better suvivial in some cancer types but not all47." (PMID 28986566, 2017). "Consequently, detection of MGMT promoter hypermethylation may be utilized as a valuable biomarker in early diagnostics and prognostication of these cancers." (PMID 28986566, 2017). "Notably, these 3 smoking-associated markers even outperformed a methylation panel of 6 cancer-related genes (p16, MGMT, DAPK, RASSF1A, PAX5- β, and GATA5) assessed in sputum samples collected 3 to 18 months prior to LC diagnosis (sensitivity and specificity of 64%)." (PMID 27924164, 2016). "MGMT has also been shown to serve as a predictor of response to alkylating agents (temozolomide and dacarbazine) that have been approved for the treatment of various cancers including brain tumors (astrocytoma and glioblastoma multiforme), melanoma, sarcoma, and Hodgkin lymphoma." (PMID 26875156, 2016). "Moreover, the hypermethylation of the CpG island within the DNA-repair protein O-6-methylguanine-DNA-methyltransferase (MGMT) gene and in the MLH1 gene is associated with a reduced gene expression observed in the majority of sporadic primary CRC cancers with microsatellite instability." (PMID 26862732, 2016). "MGMT methylation may also play a prognostic role in various cancers." (PMID 27643594, 2016). "Hence, targeting the ERp29\MGMT could be an effective strategy to overcome resistance to radiotherapy in cancer." (PMID 26420420, 2015). "It is demonstrated that cancer cells if express higher activity of O6-methylguanine-DNA methyltransferase (MGMT), a DNA repairing enzyme to remove TMZ-DNA adduct, may diminish the therapeutic efficacy of TMZ and appear to be more resistant and refractory to TMZ therapy." (PMID 25763821, 2015). "Hence, our studies prove a novel function of ERp29\MGMT in cancer cell survival against radiation." (PMID 26420420, 2015). "To further test whether celecoxib can restore temozolomide sensitivity to temozolomide-resistant cancer cells in vitro we first treated cells expressing either low or high levels of MGMT with increasing concentrations of temozolomide and measured the tumourigenic capacity using clonogenic assays." (PMID 26603103, 2015). "The weak association of G > A mutations occurring in non-CpG sites in the cancer cell exome shows that MGMT deficiency may indeed contribute to the accumulation of some of these mutations." (PMID 25638164, 2015). "Our results suggest that MGMT-kB1-LODN may provide a novel strategy for cancer therapy." (PMID 25460932, 2014). "Because the available data were not compatible, we could not evaluate the combined effects of MGMT Leu84Phe and Ile143Val on cancer susceptibility in our meta-analysis." (PMID 24086516, 2013). "While differentiation therapy has been proposed as a means to sensitize cancer cells, direct evidence linking ATRA to the modulation of MGMT expression in GBM models has been limited." (PMID 40422249, 2025).
cancer (continued). "Each subpanel corresponds to one gene (ATRX, OLIG2, MGMT, and IDH2) and displays its expression levels in tumors (red) and normal tissues (blue) across multiple cancer types." (PMID 40282990, 2025). "Initial steps include analytical validation of a serum assay panel (p-cresol, S1P, 7-HOCA, DLST, MSR1, PGAM2, and ATG5) as well as known hallmarks of cancer proteins with standardized pre-analytics and central IDH and MGMT testing." (PMID 41294712, 2025). "Thus, circHIPK3/miR-124-3p/MGMT may modulate resistance to multi-drugs in these cancers." (PMID 40061896, 2025). "For example, the PARylation of MGMT by PARP can regulate the activity of MGMT, potentially enhancing the sensitivity of cancer patients when combining alkylating agents with PARP inhibitors." (PMID 38254819, 2024). "It is well established that TMZ is significantly more effective in patients with MGMT promoter methylation, and the same approach needs to be applied with NAD inhibitors across all cancers." (PMID 38893173, 2024). "Glioblastoma cell lines that express high levels of MGMT are resistant to TMZ, highlighting the need to better understand and overcome resistance mechanisms in cancer therapy." (PMID 39409913, 2024). "MGMT directly repairs the DTIC-induced genetic lesions and confers DTIC/TMZ resistance properties to cancer cells." (PMID 37024907, 2023). "Based on current observations, tumors harbouring a combined methylation of MGMT and ERCC1 had a strong tendency towards lymph node metastasis, distant spread, perineural invasion, cancer relapse, and overall survival." (PMID 37510370, 2023). "Hence, cancer cells with high MGMT levels might be resistant to alkylating chemotherapy." (PMID 37510370, 2023). "More recently, PARP-1 was also demonstrated to play a central role in PARthanatos observed in cancer cell lines following treatment with the alkylating agents MNNG and MMS, which was dependent on the MGMT level." (PMID 36902118, 2023). "To expand the utility of this T + N + P combination treatment regimen to other cancer cell types, we treated U2OS cells that have endogenous expression of MGMT and are resistant to TMZ treatment." (PMID 35892832, 2022). "Aberrant methylation of O6-methylguanine-DNA methyltransferase (MGMT) promoter has been reported as a key event in the development and progression of cancer." (PMID 35723009, 2022). "Similar to other carcinoma, in EC various tumor suppressor gene promotors (MLH1, PTEN, p16, APC, MGMT, RASSF1, PR and CDH1) are hypermethylated, whereas oncogene promotors (BMP, CTCFL, PARP1, CASP8) are hypo- or demethylated." (PMID 35284957, 2022). "Our functional assays revealed that O6BG increased olaparib-induced DSB formation and cell apoptosis in NPC cells, supporting the therapeutic strategy of combining MGMT and PARP inhibitor in treating cancer patients." (PMID 33397362, 2021). "Clinical and demographic features, including MGMT, IDH with codel subtype, 1p/19q, IDH, sex, age, grade, histology, and cancer type, are also shown in the heatmap." (PMID 34804019, 2021). "Despite advances in finding predictive biomarkers, such as MGMT promoter methylation status, the five-year survival is still less than 3%, making GBM the deadliest of all cancers." (PMID 34202589, 2021). "DDR and related genes were found frequently methylated in human cancers, including BRCA1/2, MGMT, WRN, MLH1, CHFR, P16 and APC." (PMID 32974031, 2020). "For all analysed genes (p16, MGMT, and RASSF1), the methylation levels were found to be 5% higher in the cancer group compared to the control group." (PMID 31903158, 2020).
cancer (continued). "The scientific literature is practically absent of information regarding proteoglycan and pharmacological resistance in cancer, but Saito and colleagues did demonstrate that GBMs with high contents of GPC1 would be positively correlated to MGMT expression." (PMID 32180897, 2020). "Thus, the protective effect of MGMT could diminish the cytotoxic effects of alkylating agents, suggesting that MGMT activity is likely to be a useful marker of the sensitivity of cancer cells to alkylating agents." (PMID 33628188, 2020). "The value of PDI signature in patients separated by subtype, MGMT promoter status, 1p19q codel status, IDH status, gender, age, grade, and cancer (LGG vs. GBM)." (PMID 32023222, 2020). "MGMT and CNR1 are two classical markers for the CpG island methylator phenotype (CIMP) and they are hypermethylated in cancers." (PMID 31534549, 2019). "Since FM-HCR reporters have been successfully transfected into both primary cells and cancer cells, and the NR-1 probe is amenable to any cells from which lysates can be derived, both approaches could potentially be used for studies of MGMT activity in cancerous and normal tissue." (PMID 30811507, 2019). "Our meta-analysis was unable to find any statistical significance between HBV-positive carcinoma tissues and HBV-negative carcinoma tissues for the methylation of the remaining seven genes, including RUNX3, p14, WIF1, CDH1, PRDM2, SOCS1 and MGMT." (PMID 31772678, 2019). "In summary, in this paper we explore the role and mechanisms of TMZ–POH in MGMT downregulation, and those of MGMT downregulation in TMZ–POH’s cytotoxicity, thus proposing TMZ–POH as a potential therapeutic candidate of cancers." (PMID 29426908, 2018). "Given the importance and complicated regulation of MGMT, in this paper we focused on the role of TMZ–POH in MGMT regulation, and that of MGMT in TMZ–POH’s cytotoxicity in multiple cancer cells." (PMID 29426908, 2018). "However, since MGMT loss has been also identified in healthy colorectal tissue, this event has been referred as a “field defect”, which means it is neither necessary nor sufficient to cancer progression." (PMID 28903334, 2017). "Abnormally methylated regions in cancer-related genes such as RASSF1A, p16, RAR-β, and MGMT, provide adequate sensitivity and specificity for the detection of HNC." (PMID 27683120, 2016). "Cells that overexpress MGMT are resistant to treatment with TMZ, while inhibition of MGMT in cancer cells can increase the efficacy of treatment." (PMID 27186882, 2016). "Overcoming TMZ resistance is an urgently expected development in cancer therapeutic, several studies are also investigating avenues to overcome TMZ resistance by regulation MGMT promoter methylation or gene expression level." (PMID 27384876, 2016). "First, we targeted the following loci given the initial observation from TCGA: five imprinted domains (PEG3, H19/IGF2, DLK1/GTL2, MEST, GNAS) and four cancer genes (APC, MLL3, MGMT, ELF3)." (PMID 26338779, 2015). "Results indicated that most GSC lines with high MGMT activity (≥200 fmol/mg) showed low sensitivity to TMZ, with IC50s >300 μM, a value which is well above the peak plasma concentration reached in cancer patients (20–96 μM at a TMZ dose of 200 mg/m2)." (PMID 24593254, 2014). "For example, the possibility exists for the augmentation of MMR and the HR system in cancer cells with MGMT in an inactive state, such as in GBM with a methylated MGMT promoter, which has potential to interfere with TMZ cytotoxicity." (PMID 25061500, 2014). "When the results were statistically analyzed using paired-T test, RASSF1A, MGMT and CDKN2A showed comparable results in the cancer tissue and plasma samples." (PMID 24790823, 2014). "Inactivation of P16, MGMT and HMLH1 plays a role in the progression of various cancers, and the inactivation of them is induced by aberrant hypermethylation." (PMID 24550949, 2013).
cancer (continued). "In conclusion, genetic mutation in the Kras gene and epigenetic modification in RASSF1A, FHIT and MGMT genes in sporadic CRC are associated with the overall development of the disease and may be used as diagnostic or prognostic markers in this group of cancers." (PMID 23573237, 2013). "CAP showed anti-cancer properties in chemotherapy resistant and sensitive cells, whereas TMZ was effective only in cells with favorable MGMT status." (PMID 23704990, 2013). "Consistent MGMT and MLH1 expression was observed in serrated lesions and their complicating cancer tissues from certain patients, suggesting that the mechanism underlying the carcinogenesis of serrated lesions is more complex than expected." (PMID 24223631, 2013). "Six COPD patients developed cancer after five years from the initial COPD diagnosis at 2006–2007.We also evaluated the frequency of CDKN2A, CDH1 and MGMT promoter methylation in sputum samples of the groups under study." (PMID 22818553, 2012). "Previous studies identified hypermethyled promoter regions in some commonly methylated genes (RASSF1A, p16, MLH1, MGMT, HOXA9) in different types of cancers." (PMID 22140553, 2011). "Eight cell lines exhibit expression of the MGMT protein, including four GBM (AMC 3344, VU-28, VU-110 and T98) and four other carcinomas (A-431, HT-29, PC-3 and SW1573)." (PMID 20517307, 2010). "Several frequently methylated loci identified in early studies, for example CDKN2A/p16, CDH13, MGMT and RASSF1 remain viable markers when assessed in a larger context, providing support for their role in cancer development/progression." (PMID 18947422, 2008). "On top of that, tests for MGMT methylation vary in accuracy, and there’s no standardized cutoff to define MGMT silencing across cancer types making treatment decisions tricky." (PMID 40895460, 2025). "miR-7-5p/ABCC1/SLC7A5, miR-107/RAD51, miR-124-3p/ABCC4/SLC16A1/MGMT, miR-212-3p/ABCG2, miR-381-3p/GJA1 and miR-485-3p/SLC40A1 may modulate pathways that confer chemoresistance to cancer cells." (PMID 40061896, 2025). "Although MGMT level was not high in MM cells with chemotherapy, the transcriptional activity of MGMT could be improved by activation of the ERK signalling pathway after TMZ treatment, which may be one of the mechanisms of resistance to TMZ malignant tumour." (PMID 39873425, 2025). "Tumors with high MGMT expression often exhibit resistance to alkylating chemotherapeutic agents such as temozolomide (TMZ), carmustine (BCNU), and lomustine (CCNU), which rely on unrepaired DNA lesions to trigger cancer cell death." (PMID 40895460, 2025). "It was further discovered that TMZ selectively destroys glioblastoma cancer stem cells in MGMT-negative cell lines, indicating this protein's potential in cancer treatment." (PMID 38291266, 2024). "Notably, BRCA1 and MGMT mRNA levels were greater in the WBC RNA of the BC patients and cancer-free methylation carriers than in that of the OC patients." (PMID 38542081, 2024). "O6-methylguanine-DNA methyltransferase (MGMT) constitutes an important cellular mechanism for repairing potentially cytotoxic DNA damage induced by guanine O6-alkylating agents and can render cells highly resistant to certain cancer chemotherapeutic drugs." (PMID 37631385, 2023). "The increased expression of CD133, CD9, and CD44, along with SOX9, TUBB3, MGMT, and ABCG2, may have led the GBMs on a path of acquiring cancer-specific stemness." (PMID 36834653, 2023). "Nevertheless, MGMT blockage, an available drug in cancer therapy, attenuated only serum cytokines but not mortality in CLP with antibiotics, implying further drug administration and delivery development." (PMID 37373325, 2023). "Our observations suggest that tumors with low levels of treatment resistant cancer stem cells all respond similarly to treatment, independent of MGMT promoter methylation status." (PMID 36333778, 2022).